CXCR4 (C-X-C motif chemokine receptor 4)
Diseases named in the same sentence as CXCR4 in open-access papers (continued):
Sharing a sentence is not in itself a finding about the gene and the disease.
tumor (continued). "On the other hand, surface markers specific to tumor stem cells have not been established in renal tumors; however, it has been proposed that CXCR4 is essential for the maintenance of renal tumor stem cells, and it could be a good candidate as a specific marker of tumor stem cells." (PMID 31968688, 2020). "Thus, the reduction in N-[11C]methyl-AMD3465 uptake in the tumor after treatment with AMD3100 observed in this study is likely the result of a combination of saturation of the CXCR4 receptors by the antagonist and a reduction in T-cell infiltration by inhibition of CXCR4-mediated chemotaxis." (PMID 31802362, 2020). "Since CSCs have been demonstrated to be more resistant to chemo- and radiation therapy and thus might contribute to drug resistance and tumor recurrence, we analyzed the sensitivity of CXCR4 positive and negative cells toward cisplatin (DDP) and docetaxel (TXT)." (PMID 32232002, 2020). "Finally, gene expression profiling in two sets of CAFs after CXCR4 knockdown revealed significant alterations in the transcriptional profile, including reduced expression of IL8 and other secreted ligands that are known to be tumor microenvironmental regulators." (PMID 31663852, 2019). "This process could be attributed to the overexpression of SATB-1 in tumor cells near stimulated CAFs, which then upregulate the secretion of SDF-1, a cytokine that plays a crucial role in many types of solid tumors by initiating signaling through its receptor CXCR4." (PMID 30927928, 2019). "Thus, although disruption of tumor-stromal cell interaction by CXCR4 antagonism did not increase the efficacy of rituximab-induced antibody-dependent cellular cytotoxicity in vitro, this might be the case in vivo." (PMID 30774774, 2019). "Additionally, cells expressing CXCR4-Δcarboxy terminal domain (CTD) can exhibit epithelial–mesenchymal transition (EMT)-like changes, such as changes in stellate cell appearance, enhanced motility, and decreased cell adhesion, which are characteristic of tumor cells." (PMID 30791675, 2019). "The increased CXCR4 expression on bone metastatic cells compared to non-metastatic cells may enhance tumor cell association with the niche in a similar manner to HSC homing to the niche, in which higher CXCR4 expression is associated with more rapid engraftment and reconstitution." (PMID 29642534, 2018). "In addition, inhibitors of CXCR4, such as CTCE-9908, a small peptide analogue of SDF-1, have been demonstrated to be effective in preventing metastatic dissemination in different cancer models such as breast, oesophageal and prostate, by acting both on CSCs and on proliferating tumor cells." (PMID 29461491, 2018). "In summary, these data might hint to an ontogenetically early onset of SDF-1/CXCR4 signaling in mesenchymal and epithelial primordia of the different organs which might be the reason for SDF-1/CXCR4 expression in stem(-like) subpopulations of many different tumor entities." (PMID 30622535, 2018). "Additional transwell experiments showed that effector B cells could directly kill tumor cells in cell-cell contact via the Fas/FasL and CXCR4/CXCL12 pathways as well as perforin, while without cell contact, perforin secreted by B cells led to tumor cell cytotoxicity." (PMID 27528023, 2016). "Thus, we hypothesized that genetically modified low CXCR4-expressing tumor cells may not able to migrate through the perivascular space and will display fewer interactions with brain microvasculature." (PMID 27863376, 2016). "Thus, to investigate whether expression of any one of the two CXCL12 receptors or both in NB tumor cells could influence their selective homing, eGFP+ transduced IGR-NB8 control cells or cell lines overexpressing either CXCR4, CXCR7, or combined receptors, were injected iv in NSG mice." (PMID 25955316, 2015).
tumor (continued). "Taken together with other reports describing a role for CXCR4 in the regulation of neural stem cell function our data showing that POL5551 reduced the numbers of nestin positive perivascular cells, led us to hypothesize that POL5551 might have direct effects on tumor stem cells." (PMID 25238146, 2014). "Therefore, targeting CXCR4 not may only control tumor spread, but also may reverse drug resistance in cancer chemotherapy or endocrine therapy." (PMID 23071744, 2012). "As there is no increase in CXCR4 expression seen in the MTLn3 JP tumor cells, the response seen in MTLn3 JP tumors to high levels of CXCL12 may reflect initiation of the paracrine loop by tumor-associated macrophages, which express CXCR4." (PMID 22152016, 2011). "CXCR4 may play a role in the transition of a tumor from non-metastatic to its malignant phenotype." (PMID 19563666, 2009). "Through secretion of TGF−β and ARG2, CAFs induce M2 polarization of TAMs and expansion of Tregs, while CXCL12 produced by CAFs engages CXCR4 on T cells, forming a “chemokine barrier” that excludes CD8+ T cells from tumor nests." (PMID 40963620, 2025). "Additional immunohistochemical analyses showed that tumours that were visible on [68Ga]Ga‐CXCR4 PET/CT (n = 2) had high CXCR4 expression, and tumours that were not (n = 2) had no or mild CXCR4 expression." (PMID 40923371, 2025). "The expression level of CXCR4 in NEC patients was not significantly correlated with gender, tumor size and other clinicopathological parameters." (PMID 38524630, 2024). "Furthermore, widespread co-localization of MIF-(CD74+CXCR4) was observed in spatial transcriptomics, suggesting that the MIF signaling pathway may be a key mechanism through which MVI_Scissor+ malignant cells exert significant influence in the tumor microenvironment." (PMID 39176099, 2024). "The interactions where non-tumor cells influenced tumor cells included NAMPT → INSR, MIF → CD74 and CXCR4, GRN → SORT1, and CD99 → CD99." (PMID 39095793, 2024). "We examined chemokine receptor expression of IgG+plasma cells in obese tumor samples and non-obese tumor samples, including CXCR3, CXCR4 and CXCR5, and found that IgG+plasma cells in obese CRC highly expressed CXCR4." (PMID 38311726, 2024). "EVs derived from osteotropic LCP melanoma cells appear to stimulate the osteotropic behavior of SK-Mel28 and WM-266, non-osteotropic tumor cells, toward bone in a CXCL12-stimulated manner through the atypical chemokine receptor 3 (ACKR3)/CXCR4 axis." (PMID 39698539, 2024). "LY2510924 is stable in in vivo experiments and inhibits tumor growth in human xenograft models developed with RCC, non-Hodgkin lymphoma, lung, and colon cancer cells that express functional CXCR4." (PMID 36293358, 2022). "The expression of stem cell markers was also evaluated on primary tumor cells from 55 PDAC patients who underwent pancreatectomy with radical intent, revealing that CXCR4+/CD133+ and CD24+ cells, but not ESA+CD24+CD44+, are independent predictors of mortality." (PMID 36142575, 2022). "The multivariate analysis confirmed tumor grade, adjuvant CT/RT, and HST (or CXCR4+CD133+ cells but not CXCR4+CD133− and CXCR4+ cells) as independent predictors of PDAC mortality." (PMID 36142575, 2022). "Furthermore, fibrogenic factors, including PDGFRβ, CXCR4, and TGFB1, which may be expressed by the stromal cells or the reprogrammed brain cells, can potentiate fibrosis in the metastasis brain environment which, in turn, contributes to increased angiogenesis and tumor growth." (PMID 36216799, 2022). "CXCR4 is highly expressed in most CSCs, and the combination of nonpeptide CXCR4 antagonists with etoposide and cisplatin reduces CSC proliferation and inhibits tumor growth." (PMID 35740975, 2022). "The E/NSCLC patients, one with 3.4% EGFR+ and 10.5% CXCR4+ serum sEVs and the other with 4.1% EGFR+ and 12.6% CXCR4+ serum sEVs, both had nearly negative EGFR staining and low CXCR4 staining in the primary tumor tissue." (PMID 35269297, 2022).
tumor (continued). "Although, similar to its partner CXCR4, CXCR7 expression can be regulated by epigenetic mechanisms involving miRs in different tumor types; to date, no data in the literature have demonstrated the involvement of a miR to regulate CXCR7 expression in CRC." (PMID 35406582, 2022). "Out of 6 tumors of mice treated with the CXCR4 antagonist AMD3100, 2 showed focal intra- or peritumoral vessels while there was no tumor with distributed intratumoral vessels as seen in control mice." (PMID 35717322, 2022). "Independent of the presence or absence of expression in the tumour cells, SST and CXCR4 were often strongly expressed on the tumour capillaries." (PMID 35799158, 2022). "Orthotopic tumour models were developed from CD44+, CD44+ α2β1+, ALDH+ CD44+ α2β1+ and ALDH+ CD44+ CXCR4+ CD24+ cells with or without HOXB9 knockdown." (PMID 34247196, 2021). "On the other hand, CXCR4, the receptor of CXCL12, showed heterogenous expression patterns and its expression was not correlated with the existence of senescent tumor cells in CRC tissues." (PMID 33643790, 2021). "CXCR4 and ACKR3 were found upregulated in tumor core GBM cells (without distinction of necrotic and/or angiogenic features) compared to infiltrating area and healthy tissue, which is supportive of the IvyGAP data." (PMID 35008294, 2021). "Immunofluorescence staining of AQP1, CXCR4 and MAP2 of the primary tumor revealed AQP1 expression in some but not all tumor areas, as well as staining of vascular structures in which AQP1 occurs physiologically." (PMID 33671521, 2021). "A significant negative linear correlation was found between tumor growth and CXCL12 (r = −0.573, r2 = 0.329, p = 0.008, n = 20), while a positive linear correlation emerged with CXCR4 (r = 0.448, p = 0.037, r2 = 0.201, n = 23)." (PMID 34834449, 2021). "In human iCCA tissues TNF-α is mainly expressed in infiltrating macrophages, while CXCR4 is present in cancer cells but not in non-neoplastic ducts and CXCL12 in stromal fibroblasts and, to a lesser extent, in tumor cells." (PMID 32784743, 2020). "Although CXCR4 expression is a prognostic factor in several human tumor types, none of the CXCL12/CXCR4/CXCR7 has yet been definitively validated as a tumor driver." (PMID 33363463, 2020). "Mice were administrated with anti-CXCR4 scFvs (aCX73 and aCX82, 10 mg/kg), the negative control antibody (Her2-13C1, 10 mg/kg) and DDP (2 mg/kg) as a positive control when the tumor volumes were about 100 mm3." (PMID 33392074, 2020). "This indicates that microenvironmental cues within the tumor can trigger heterogeneity in CSCs and CD133+CXCR4+ and CD133+CXCR4- are not a distinct subpopulations but a gradient of stemness phenotypes." (PMID 33339340, 2020). "As an important pre-requisite to CXCR4 directed therapy, [68Ga]Pentixafor PET/CT enables the non-invasive evaluation of receptor expression of all tumor lesions." (PMID 31475113, 2019). "Under s-μg, the tumor marker EWS/FLI1 is intensified, while targeting CXCR4, which influences adhesion proteins, did not affect spheroid formation." (PMID 31810195, 2019). "As important findings, tumor marker EWS/FLI1 was more intensely expressed on the gene and protein level, and CXCR4, although highly upregulated under s-μg, does not seem to affect spheroid formation, as we showed by its inhibition." (PMID 31810195, 2019). "GLI1 can be activated non-classically by other pathways, such as PI3K-AKT, CXCR4, RAS, and TGF-beta, in tumor cells, independent of SHH1." (PMID 31783569, 2019). "Examples of other non-chemokine receptors known to interact with CXCR4 include the cannabinoid receptor CB2, with implications for tumor progression." (PMID 31507535, 2019). "FLT-3 ligand-induced tumor mice resulted in an increase in all splenic cDC resident and migratory subsets negative for CXCR4, with 30.4% of CXCR4− cDCs being CD8α+, 59.5% were CD11b+, and 42.2% were CD103+." (PMID 30489627, 2018).
tumor (continued). "However, it remains unknown how the generation and secretion of SDF1/CXCR4 molecules correlate in the same cancer cell and how they interact with upstream and downstream pathways, e.g., AnnexinA7 and VEGFC/D-VEGFR3/NRP2 during tumor development and progression." (PMID 29783989, 2018). "This chemokine, via interaction with the receptors CXCR4 and CXCR7, induces attraction and activation of immune and non-immune cells, migration and adhesion of tumor cells to the protective tissue microenvironment." (PMID 28635657, 2017). "To provide more evidence that IL-2 augments the TDLN B cell killer/effector function via the CXCR4/CXCL12 axis, we performed experiments to compare the CXCL12 production by 4T1 tumor cells in the presence or absence of IL-2." (PMID 27528023, 2016). "Our study also found that effector B cells can kill tumor cells via cell-cell contact utilizing the Fas/FasL and CXCR4/CXCL12 pathways as well as perforin, while without cell contact, perforin secreted by B cells can also lead to tumor cell cytotoxicity." (PMID 27528023, 2016). "Therefore, aberrant expression of NF-κB induced by intrinsic or extrinsic factors may contribute to create a tumor microenvironment where a negative feedback loop inhibiting CXCR4/CXCL12 and VLA4/VCAM1 cellular communication axes allows for the maintenance of malignant cells." (PMID 27594840, 2016). "Xenograft studies showed that overexpression of CXCR4, but not a dominant-negative mutant of it, in the MDA-MB-231 cells prevented the invasive growth of primary tumor and lung metastasis from inhibition by knockdown of KLF8." (PMID 26993780, 2016). "Immunohistochemical analysis further showed that poly I:C treatment significantly increased tumour cell PSA expression, while not affecting AMACR and almost wiping out CXCR4 staining from cancer cells." (PMID 25444175, 2015). "CXCL12 expression was markedly absent, and CXCR4 and CXCR7 expression were more pronounced in human PDAC tumor cells." (PMID 24594697, 2014). "Immunohistochemical studies showed that in GBM CXCR4 and CXCL12 expression does not co-localize with tumor proliferating cells (identified by MIB-1 expressing cells) but they are both mainly localized in hypoxic regions, characterized by necrosis." (PMID 24904289, 2014). "We demonstrated, for the first time, that hypoxia upregulated CXCR4 but not CXCR7 expression in tumor cells and that the CXCR4 receptor protein level remains high at the cell membrane when the tumor cells return to normoxia for up to 48 hours." (PMID 24629239, 2014). "Although clearly detectable, the percentages of CD45+ cells found in the different MIN-O and 4T1 tumor tissue samples are not likely to influence the CXCR4 based discrimination between the MIN-O and the 4T1 tumor lesions." (PMID 23326303, 2013). "Having shown that SDF-1α/CXCR4 signaling is involved in wound-promoted tumor growth in BALB/c animals, but not in BALB/c nu/nu animals, we wondered how wound-promoted tumor growth varied between strains and if and SDF-1α levels would shift concordantly." (PMID 23593347, 2013). "The expression levels of CCR7, CXCR4 and VEGF-C did not correlate with the clinicopathological parameters, including those of age, gender, tumor size and histological grade (P>0.05)." (PMID 23761820, 2013). "Studies have also demonstrated that the activation of CXCR4 by CXCL12 stimulates a specific and significant proliferative response in GSCs, but not in differentiated tumor cells." (PMID 23961808, 2013). "To further confirm these findings in non-tumor cells, we transiently transfected WT-CXCR4 or MUT-CXCR4 into HEK293 cells, which are negative for expression of LMP1 and CXCR4." (PMID 23472069, 2013). "Inhibition of tumour cell cytokine production by stable expression of shRNA to CXCR4 in IGROV-1 cells did not influence the attachment of cells to the mesentery but delayed neovascularization and reduced tumour deposit size." (PMID 22322968, 2012).
tumor (continued). "It was observed that CXCR4 and CCR7 expression in metastasis tumor was even higher, although no significant distinction was evident." (PMID 20181250, 2010). "Although the role of CXCL12 in the promotion of invasive growth is well documented and the intracellular signals triggered by CXCR4 activation have been extensively investigated, the role of CXCL12/CXCR7 axis in regulating tumor growth of HCC is not yet known." (PMID 20380740, 2010). "Tumor tissue from HCC patients with (n = 43) and without (n = 138) bone metastasis was subjected to immunohistochemical staining for CXCR4 using tissue microarrays." (PMID 19508713, 2009). "In contrast to currently available anti-CXCR4 antibodies, the novel rabbit monoclonal antibody UMB-2 yielded highly effective plasma membrane staining of tumor cells without any detectable immunostaining of cell nuclei." (PMID 19116653, 2008). "There was also no combination of variables, for example, only CXCR4 and SFD-1-positive tumours compared with others, which resulted in a significant influence on patient prognosis (data not shown)." (PMID 17245339, 2007). "Moreover, the knockdown of MDMX in primary xenograft tumors in the tumor microenvironment (TME), but not in cell culture, correlates with a lower expression of the well-studied metastasis-promoting receptor CXCR4." (PMID 39766093, 2024). "Therefore, although the expression level of CXCL12, CXCR4 and CXCR7 has been considered a prognostic factor in several human tumor types, none of the actors of this axis have yet been definitively validated as pro-tumoral factors." (PMID 35406582, 2022). "The tumor infiltrating CD4+ and CD8+ T cells also had a mature immunophenotype, as they were more often CD57 positive and CD27 negative, as well as expressing the chemokine receptor, CXCR4." (PMID 35003893, 2022). "Conversely, in MUC-1, RGZ did not modulate the CXCL12/CXCR4 axis, suggesting that the up-regulated CXCL12 in response to RGZ might be active only in the primary tumor but not in the metastatic cells." (PMID 34834449, 2021). "In some rodent models, tumor and non-tumor cells in the TME (e.g., leukocytes, fibroblasts, endothelial cells) secrete inflammatory mediators such as interleukin (IL)-1, tumor necrosis factor (TNF)-α, IL-6, IL-8, IFN-α, IL-10, IL-12, TGF-β, and CXCR4." (PMID 34200240, 2021). "Interestingly, bioinformatic analysis of microarray data deposited in the GEO database revealed a positive correlation between MET and SNAIL expression in 158 RMS tumor samples derived from patients but not between SNAIL and CXCR4." (PMID 32664538, 2020). "In silico criteria for tumor selection may include the presence of GM-CSF, IL-3 and FLT3-L, ligand expression of chemokine receptors CXCR4, CCR7, and CXCR3 and the absence of very high GM-CSF level." (PMID 33013879, 2020). "The majority of tumor-infiltrating mast cells expressed CXCR4 but not CCR2, CCR4, CCR5, CCR7, CXCR1, CXCR2 or CXCR7, while, mast cells in peritumoral or non-tumor tissues showed lower CXCR4 expression." (PMID 30808413, 2019). "Interestingly, while Cxcr4 inhibition leads to suppression of Mist1-derived tumor growth, there is compensatory activation of the CCK2R lineage, which we showed was negative for Cxcr4 expression." (PMID 29340033, 2017). "The C6 tumor is clearly visible in the control animal, but not in the Plerixafor® treated animal, indicating that the drug is able to compete with the PET tracer for the binding site of CXCR4." (PMID 27896627, 2017). "Histological analyses revealed that the dramatic inhibition of the tumor invasion into the surrounding tissues by knockdown of KLF8 (compare I with U) was also well prevented by overexpression of CXCR4, but not its dN20 mutant (compare I+CXCR4 or I+dN20 with I)." (PMID 26993780, 2016). "Interestingly, two patients (#2, #6) had no detectable CXCR4-expression by PET/CT, whereas receptor expression was maximal on all tumor cells (IRS 10 and 12, respectively)." (PMID 26843617, 2016).